SPP1 (secreted phosphoprotein 1)
Diseases named in the same sentence as SPP1 in open-access papers (continued):
Sharing a sentence is not in itself a finding about the gene and the disease.
breast cancer (continued). "Under the chemotherapy, JNK pathway activation triggers osteopotin (or SPP-1) and TNC secretion, then induces chemoresistance and metastasis in breast cancer." (PMID 36906534, 2023). "SPP1+TAM subpopulation was initially found in colorectal cancers (CRC), and later in lung and breast cancers." (PMID 38347955, 2023). "An increasing number of research articles have shown that SPP1 and CSF1 exhibit the same expression trend in multiple cancer types, including liver cancer, breast cancer, thyroid cancer, and lung cancer." (PMID 37097499, 2023). "Macrophage subsets that express SPP1, TREM2 and FN1 anti-inflammatory TAMs were found in breast cancer." (PMID 38347955, 2023). "Higher MMP1, SDC1, SPP1, and CD24 expression was correlated with worse overall survival (OS) and relapse-free survival (RFS) in breast cancer patients." (PMID 35037689, 2022). "In breast cancer tissue samples, MMP1, SDC1, CD24, and SPP1 showed higher protein expression compared with that in tumor-adjacent tissues, and their expression was positively correlation with tumor subtype and grade." (PMID 35037689, 2022). "The cytokine Osteopontin (OPN, SPP1) constitutes the most abundantly secreted phosphoprotein in breast cancer, which also supports invasive behavior." (PMID 36175970, 2022). "In the present study, we evaluated tissue SPP1 mRNA and OPN protein expression as markers of recurrence in estrogen receptor- positive (ER+) breast cancer tissue." (PMID 31996744, 2020). "Our results reveal that SPP1 and TNC are directly induced by the c‐Jun transcription factor in breast cancer cells in response to stress and serve as essential mediators of chemotherapy resistance." (PMID 30190333, 2018). "Considering this, we evaluated the clinical relevance of SPP1 and TNC expression in tumors, by analyzing transcriptomic profiles from breast cancer patients that were annotated for lung metastasis." (PMID 30190333, 2018). "Consistently, we observed a considerable downregulation of SPP1 and TNC levels in breast cancer cells from primary patient‐derived effusion samples treated with JNKi." (PMID 30190333, 2018). "Recent studies reported that SPP1 overexpression had been found in numerous cancers including HNC, breast cancer, lung cancer, gastric cancer, hepatocellular carcinoma, colorectal cancer etc." (PMID 26857387, 2016). "Seven over-expressed breast cancer genes, namely BCAR1, HSD17B1, MMP14, PLAU, SFRP2, SPP1 and VCAN, had increased promoter methylation and their promoters contained the tumor-specific hypermethylated A-6 or A-7 HMRs." (PMID 25706888, 2015). "Osteopontin (OPN), also known as secreted phosphoprotein 1 (SPP1) and originally identified in osteoblasts, is transcriptionally regulated by BRMS1 in breast cancer." (PMID 22927944, 2012). "We therefore developed a new macrophage-specific SPP1 TAM signature (PLAUR, SLC11A1, BRI3, FBP1, C15orf48) using publicly available scRNA-Seq data from lung, colorectal and breast cancers and validated the signature using multiple independently published scRNA-Seq datasets." (PMID 41415295, 2025). "Moreover, changes in the promoter methylation status of the Cdh2 and Spp1 genes, as a direct or indirect effect of Mbd2 deletion and subsequent binding by a transcriptional repressor, may also constitute a possible mechanism for regulating these genes in breast cancer." (PMID 38556549, 2024). "Studies have demonstrated that SPP1 could interact with CD44 in prostate cancer, GBM, and breast cancer." (PMID 35067176, 2022). "CSF-1 stimulation increased spp1 gene expression only in the C3-223-Fms mammary cancer cells but not in the NIH 3T3." (PMID 36555673, 2022). "Third, four hub genes that could have important key functions in tumor growth in breast cancer, MMP1, SDC1, CD24, and SPP1, were identified using GEO and TCGA public datasets as potential prognostic biomarkers." (PMID 35037689, 2022).
breast cancer (continued). "The major transcriptional effects of DMHCA were linked to transrepression of a network of LXR-responsive genes, including PTGS2, S100A9, SPP1, CD14, CCL5 and ANXA1, which are overexpressed in MDSC and in a significant proportion of breast cancers, where they denote poor survival." (PMID 33780491, 2021). "SPP1 was found to be regulated by c-Jun N-terminal kinase (JNK) signaling pathway and could promote the lung metastasis of breast cancer." (PMID 33753985, 2021). "For example six SEREX antigens identified in serum from breast cancer patients (RAD50, PARD3, SPP1, SAP30BP, NY-BR-62, and NY-CO-58) could identify breast cancer patients from healthy donors with 70% sensitivity and 91% specificity." (PMID 33976232, 2021). "Other researchers also concluded that altered expression of some genes (RRM2, SPP1, MMP9, Arf1) could be involved in increased cell proliferation of adipose tissue in breast cancer risks." (PMID 34657612, 2021). "DAB2, MMP14, and SPP1 were also consistently expressed in CD68+ microglia/macrophages in patient-derived breast cancer BrM (n = 4), while their expression was absent from the patient-matched blood." (PMID 31501884, 2020). "Moreover, when we analyzed SPP1 and TNC expression in human breast cancer metastasis samples ranked according to JNK signature score, a marked increase in expression of SPP1 and TNC was observed in metastasis samples with high JNK activity (Fig EV4B)." (PMID 30190333, 2018). "Moreover, our results provide rationale for considering JNK inhibition as a strategy to simultaneously repress the expression of SPP1 and TNC and thus improve therapeutic responses of breast cancer to chemotherapy." (PMID 30190333, 2018). "In contrast, delivery of antimiR-218-5p decreased Wnt activity and the expression of metastasis-related genes, including bone sialoprotein (BSP/IBSP), osteopontin (OPN/SPP1) and CXCR-4, implicating a Wnt/miR-218-5p regulatory network in bone metastatic breast cancer." (PMID 27738322, 2016). "By this approach, we consistently observed in all the three cohorts that the level of SPP1 and ALCAM mRNA expression enables the discrimination of good vs bad outcome in all ‘high-risk’ breast cancer patients showing low or no ESR1 and HER2 expression." (PMID 20736952, 2010). "SPP1 when expressed with IL11 has been shown to promote metastasis of breast cancer cells to the bone but not to the adrenal medulla." (PMID 17430594, 2007). "The apoptotic genes SPP1 and SFRP1 are candidate tumor suppressors for various cancers; AXL gene is a proto-oncogene, and NOL3 (ARC, apoptosis repressor with CARD domain) is induced in human breast cancer and confers chemo- and radiation-resistance." (PMID 19455236, 2007). "Interestingly, the JAK–STAT pathway was previously reported to be downstream signaling of SPP1 in murine mammary epithelial tumor and breast cancer, and our GSEA results also showed that the JAK–STAT signaling pathway had significant enrichment with SPP1 high‐expression phenotype." (PMID 35593388, 2022). "Importantly, disruption of either JNK activity or expression of SPP1 or TNC sensitizes mammary tumors and metastases to chemotherapy, suggesting a potentially useful combinatorial treatment strategy to target metastatic breast cancer." (PMID 30190333, 2018). "Moreover, chemotherapy treatment leads to JNK‐mediated induction of SPP1 and TNC in metastatic breast cancer cells, indicating that, apart from its intended function as a cytotoxic agent, chemotherapy may actually reinforce the establishment of a metastatic niche via the JNK signaling pathway." (PMID 30190333, 2018).
lung carcinoma (193 papers, 2005 to 2026). "More interestingly, overexpression of SPP1 is associated with poor outcomes in ALK fusion lung cancer patients." (PMID 40883281, 2025). "Metastasis—the leading cause of cancer mortality and a common feature of lung cancer—is notably facilitated by SPP1." (PMID 40559389, 2025). "SPP1, secreted by tumor-associated macrophages (TAMs), enhances cancer cell migration and invasion, as demonstrated in A549 lung cancer cells." (PMID 40761787, 2025). "The top candidate exosomal proteins associated with lung cancer, based on the number of publications supporting the association, included SPP1, CD44, ALB, SPARC, CAT, GAPDH, and CADM1." (PMID 39766023, 2024). "The bioinformatics-based association analysis identified candidate exosomal proteins associated with lung cancer, including SPP1, CD44, ALB, SPARC, CAT, GAPDH, and CADM1." (PMID 39766023, 2024). "Based on the EMTome database, a metastatic analysis revealed an association between SPP1 and metastasis in lung cancer." (PMID 38329443, 2024). "Another study suggested that there was a direct association between SPP1 and KRAS mutation in lung cancer and that SPP1 deficiency had a protective effect on patients with KRAS mutation in lung cancer." (PMID 38919629, 2024). "In late NSCLC downregulation of contractile genes such as TAGLN were also observed, but others such as MMP1, MMP9 and SPP1 were found to be upregulated, which have functions in matrix remodelling and invasion and are linked to poor prognosis in lung cancer." (PMID 38582812, 2024). "SPP1 expression in tumor-associated macrophages (TAMs) has drawn attention in various malignancies beyond lung cancer." (PMID 39727934, 2024). "Conversely, in chronic disease states increased SPP1 expression is thought to have the opposite effect, as it decreases survival time for patients with lung cancer and is associated with increased Irritable Bowel Disease symptoms." (PMID 37009487, 2023). "To date, scRNA studies have revealed several new targets in lung cancer and brought new treatment options to immunotherapy such as TREM2+, SPP1+ and C1Q+ TAMs, which are associated with the malignant progression of lung cancer." (PMID 37187731, 2023). "On the other hand, previous study regarding SPP1 expression in lung cancer generally provides positive association with poor outcomes, which is not concordant with our current study." (PMID 37139160, 2023). "As we previously discovered, FSTL1 can regulate the progression of lung cancer by interacting with secreted phosphoprotein 1 (SPP1), and the distribution of molecular molecules associated with BMP and TGF‐β signalling is the opposite." (PMID 36807490, 2023). "SPP1 had a high expression profile in the TCGA lung cancer cohort compared to healthy subjects and was associated with poor prognosis in lung cancer patients." (PMID 37427097, 2023). "The overexpression of the SPP1 was associated with the growth and stage of lung cancer, and lymph node metastasis." (PMID 36052170, 2022). "The SPP1 overexpression is associated with aggressive phenotypes of lung cancer and recently was correlated with afatinib resistance and shorter overall survival in NSCLC patients." (PMID 35887120, 2022). "Reportedly, SPP1 plays an important role in mediating macrophage polarization and facilitating immune escape in lung cancer, and MYC is an oncogene encoding a transcription factor and participating in multiple metabolic pathways that induce cancer progression." (PMID 36091047, 2022). "SPP1 gene (encoding secreted phosphoprotein 1) was identified as a pronouncedly upregulated gene in drug-resistant lung cancer." (PMID 33996808, 2021). "To validate this observation in cells, we treated the cells with a DNA methylation inhibitor 5-azacitidine, which indeed caused significant SPP1 upregulation in lung cancer cells." (PMID 33996808, 2021). "Research has shown that secreted phosphoprotein-1 (SPP1) is essential in MPE associated with lung cancer." (PMID 24758329, 2014).
lung carcinoma (continued). "Few investigators have studied the diagnostic and prognostic value of SPP1 in MPE associated with lung cancer, but data on SPP1 on cancer progression is increasing in recent years." (PMID 24758329, 2014). "Notably, both experimental and human invasive lung cancers have exhibited an overexpression of SPP1, which has been associated with unfavorable survival outcomes." (PMID 38329443, 2024). "This indicates that the up-regulation of SPP1 in COPD might be associated with the increased risk of lung cancer in these patients." (PMID 38612871, 2024). "In addition, studies have demonstrated that high SPP1 expression in macrophages promotes lung cancer invasiveness and is associated with a worse clinical outcome in multiple cancer types." (PMID 37187731, 2023). "Similarly, it has been reported to upregulate in many cancers, such as osteosarcoma, gastric cancer, oral squamous cell carcinoma, lung cancer, and overexpressed SPP1 was associated with poor prognosis and survival in cancers." (PMID 37185487, 2023). "SPP1 connects with tumor-associated macrophage (TAMs) polarization in lung cancer." (PMID 36292719, 2022). "Moreover, SPP1 plays a crucial role in epithelial–mesenchymal transition, and high SPP1 expression levels have also been associated with metastasis formation in colorectal cancers, lung cancers and melanomas." (PMID 33562105, 2021). "In this study, we identified the secreted phosphoprotein 1 (SPP1) as a potential gene associated with a poor diagnosis of lung cancer patients using the Cancer Genome Atlas analysis, which suggested that the expression of SPP1 in tumor tissues was significantly higher than normal tissues." (PMID 33996808, 2021). "The results of the study could provide insight on SPP1 as a potential new diagnostic and therapeutic target in lung cancer." (PMID 33996808, 2021). "The pro‐fibrotic and tumour‐supporting roles of SPP1+ TAMs in lung cancer are becoming increasingly evident." (PMID 40395129, 2025). "Spp1+ expression in lung carcinoma TAMs that coexpress other protumorigenic markers correlated with a worse overall clinical outcome." (PMID 40865052, 2025). "This study investigates how RT affects SPP1 expression in macrophages and explores the potential of targeting SPP1 to overcome RT resistance in lung cancer." (PMID 41221295, 2025). "As we refine our understanding of this complexity, SPP1+ TAMs in lung cancer offer a compelling lens through which to study the interface between inflammation, fibrosis, and malignancy." (PMID 40395129, 2025). "In lung cancer cells, SPP1 interaction with ανβ3 integrin was found to increase their preferential migration to the bone matrix." (PMID 39231761, 2025). "KRT81, SPP1, PCDH7, SLC2A1, and TET1 are associated with poor prognosis and survival outcomes, providing novel insights for exploring lung cancer biomarkers." (PMID 41415280, 2025). "The protein SPP1, known for its upregulation of PD-L1, contributed to lung cancer’s ability to evade immune detection." (PMID 39494300, 2024). "Due to its biological functions related to immune regulation, the role of SPP1 in the progression of various tumors, including penile cancer, ovarian cancer, lung cancer, and intrahepatic cholangiocarcinoma, has been gradually discovered." (PMID 38731915, 2024). "Increased expression of SPP1 predicts poor prognosis in esophageal cancer, colorectal cancer, lung cancer, ovarian cancer, and glioma." (PMID 39516356, 2024). "Conversely to the observations above, mono-derived SPP1+ TAM have been recently identified associated to protective CXCL13+ T cell responses and highly correlated with plasma B cells, indicating a protective SPP1+ TAM role in human lung cancer." (PMID 37342322, 2023). "It was validated at the cellular level that SPP1 facilitates lung cancer progression, migration, and invasion." (PMID 37427097, 2023).
lung carcinoma (continued). "Here, we show that PI4K2A stabilizes AXL and coordinates exocytic and endocytic trafficking of SPP1 and its receptors, respectively, to activate a protumorigenic autocrine loop in mesenchymal lung cancer cells." (PMID 36757799, 2023). "Meanwhile, in a fibrotic microenvironment, the binding of SPP1 to ITGAV inhibits the apoptosis of lung cancer cells." (PMID 37874419, 2023). "A set of genes involved in epithelial cell growth (ERBB2, EGF, and FGF2) and Plasminogen (PLG) were connected to Cancer and Lung cancer in the Year 2 SPP1 network." (PMID 37513116, 2023). "SPP1 has been shown to be involved in resistance to chemoradiotherapy for several solid cancers, including lung cancer." (PMID 37190178, 2023). "In lung cancer, the expression levels of CSF1 and SPP1 are increased and associated with the carcinogenesis and prognosis of patients." (PMID 37097499, 2023). "This indicates that SPP1 plays an extremely important role in the progression of lung cancer and also provides strong supporting evidence for our findings." (PMID 36688087, 2023). "In lung cancer, increased serum SPP1 concentrations after radiotherapy predicted a worse clinical course, suggesting the possible involvement of SPP1 in radioresistance." (PMID 37190178, 2023). "The upregulation of SPP1 can promote the proliferation, migration and invasion of lung cancer cells, and increase the resistance of lung cancer to cisplatin." (PMID 37189418, 2023). "With regard to circulating SPP1, more data are available for pleural mesothelioma than for lung cancer." (PMID 37190178, 2023). "SPP1 expression in TAMs has also been of interest regarding malignant tumors other than lung cancer." (PMID 37190178, 2023). "Subsequent studies were unrelated to lung cancer, but many indicated the SPP1-related chemoresistance and radioresistance of cancer cells." (PMID 37190178, 2023). "In this review, we summarize the significance of TAMs in lung cancers and discuss the importance of SPP1 as a new marker for the protumor subpopulation of monocyte-derived TAMs in lung adenocarcinoma." (PMID 37190178, 2023). "SPP1, a multifunctional secretory acidic glycoprotein highly expressed in lung cancer, mediates macrophage polarisation and tumor immune evasion." (PMID 37745301, 2023). "We evaluated the expression of SPP1 by TAMs in lung cancer specimens (228 cases of adenocarcinoma and 103 cases of squamous cell carcinoma) using double-IHC with anti-SPP1 and anti-macrophage antibodies." (PMID 37190178, 2023). "High expression of SPP1 was primarily owing to its decreased methylation in lung cancer, besides, SPP1 can affect the metastasis and chemoresistance of lung cancer cells and thus was associated with poor prognostic and survival in patient with lung cancer." (PMID 37185487, 2023). "Using the HLCA as a reference for the study of disease, we identify shared cell states across multiple lung diseases, including SPP1+ profibrotic monocyte-derived macrophages in COVID-19, pulmonary fibrosis and lung carcinoma." (PMID 37291214, 2023). "Most reports that discuss SPP1 expression in lung cancer have focused specifically on expression in cancer cells." (PMID 37190178, 2023). "In this review, we summarize the significance of TAMs in lung cancers and discuss the importance of SPP1 as a new marker for the protumor subpopulation of TAMs in lung adenocarcinoma." (PMID 37190178, 2023). "Previous works have demonstrated that SPP1 is overexpressed in various cancers (such as nonsmall cell lung cancer and ovarian cancer) and involved in the progression and metastasis of cancer." (PMID 37122535, 2023). "Lung cancer patient-derived EVs mRNA showed upregulation of SPP1, VEGFA, and POSTN as compared to lung cancer with bone metastasis patients." (PMID 36424413, 2022).